NSFL1C (NSFL1 cofactor)
Description:
Reduces the ATPase activity of VCP (By similarity). Necessary for the fragmentation of Golgi stacks during mitosis and for VCP-mediated reassembly of Golgi stacks after mitosis (By similarity). May play a role in VCP-mediated formation of transitional endoplasmic reticulum (tER) (By similarity). Inhibits the activity of CTSL (in vitro). Together with UBXN2B/p37, regulates the centrosomal levels of kinase AURKA/Aurora A during mitotic progression by promoting AURKA removal from centrosomes in prophase. Also, regulates spindle orientation during mitosis.
Synonyms: UBXN2C; dJ776F14.1; p47; UBXD10; UBX1
Tractability: Small molecule: a structure with a bound ligand is known. Antibody: the Human Protein Atlas places it where antibodies can reach. PROTAC: ubiquitination databases record sites on it; its protein half-life has been measured.
Gene: Protein-coding gene on chromosome 20 (1,442,162 to 1,473,842, reverse strand). Ensembl gene ENSG00000088833.
Subcellular location: Nucleus; Golgi apparatus, Golgi stack; Chromosome; Cytoplasm, cytoskeleton, microtubule organizing center, centrosome
Subcellular location (Human Protein Atlas): Nucleoplasm; Cytosol; Plasma membrane
Pathways (Reactome):
Signal Transduction: RHOH GTPase cycle
Gene Ontology:
Molecular function: protein binding; ubiquitin binding
Biological process: establishment of mitotic spindle orientation; negative regulation of protein localization to centrosome; positive regulation of mitotic centrosome separation; autophagosome assembly; Golgi organization; membrane fusion; nuclear membrane reassembly; proteasome-mediated ubiquitin-dependent protein catabolic process; ubiquitin-dependent protein catabolic process
Cellular component: VCP-NSFL1C complex; chromosome; cytoplasm; cytosol; nucleus; centrosome; Golgi stack
Genetic constraint (gnomAD): Loss-of-function variants: 10 observed, 30.74 expected, observed/expected ratio (o/e) 0.33, 90% interval 0.2 to 0.55. The upper end of that interval is the gene's LOEUF score, 0.55, which puts it in group 2 of 6, group 1 being the genes least tolerant of losing a copy. Missense variants: 367 observed, 421.41 expected, observed/expected ratio (o/e) 0.87, 90% interval 0.8 to 0.95. Synonymous variants: 155 observed, 165.24 expected, observed/expected ratio (o/e) 0.94, 90% interval 0.82 to 1.07.
Homologues: Orthologues: chimpanzee NSFL1C (100% identical), macaque NSFL1C (99% identical), guinea pig NSFL1C (98% identical), pig NSFL1C (98% identical), rabbit NSFL1C (97% identical), dog NSFL1C (97% identical), rat Nsfl1c (96% identical), mouse Nsfl1c (96% identical), zebrafish nsfl1c (72% identical), tropical clawed frog NSFL1C (69% identical), Drosophila melanogaster p47 (39% identical), Drosophila melanogaster CG42383 (31% identical), and 1 more. Paralogues in human: UBXN2B (46% identical), UBXN2A (25% identical), UBXN11 (20% identical).
Diseases named in the same sentence as NSFL1C in open-access papers:
NSFL1C is named in the same sentence as 7 diseases in open-access papers, as found by Europe PMC text mining. Sharing a sentence is not in itself a finding about the gene and the disease. The quoted sentences say what the papers report.
Becker muscular dystrophy (1 paper, 2020). Becker muscular dystrophy (BMD) is a neuromuscular disease characterized by progressive muscle wasting and weakness due to degeneration of skeletal, smooth and cardiac muscle. "We checked for overlap with protein lists in recent reports and found overlap regarding SOD and NSFL1C in a report providing muscle biopsy changes in DMD versus normal versus Becker muscular dystrophy." (PMID 32592467, 2020).
breast carcinoma (1 paper, 2013). "NSFL1C is a substrate of EGF signaling during breast cancer development." (PMID 23555679, 2013).
colon adenocarcinoma (1 paper, 2022). "Mutations of SKIDA1, CLK1, NSFL1C, OR2A5, EDEM3, and OR51V1 were associated with significant deregulation of DDX20 gene expression pattern in colon adenocarcinoma patients." (PMID 36011315, 2022).
neuroblastoma (1 paper, 2020). Neuroblastoma (NB) is the most common solid, extracranial childhood tumor. "Furthermore, pull-down of the AMPylated proteins from neuroblastoma cells under FICD E234G OX conditions revealed a general increase in AMPylation including proteins such as CTSB, TPP1, CAPZB, and NSFL1C, which were found AMPylated in COs." (PMID 31980631, 2020).
NSFL1C also shares sentences with these, for which no sentence is quoted: prostate carcinoma (1 paper); prostate tumor (1); tumor (1).